UCP1 (uncoupling protein 1)
Diseases named in the same sentence as UCP1 in open-access papers (continued):
Sharing a sentence is not in itself a finding about the gene and the disease.
Lewis lung carcinoma (2 papers, 2021 to 2022). "In particular, PTHrP induced UCP1 expression, promoting cachectic phenotypes in a Lewis lung carcinoma (LLC) model of cancer cachexia." (PMID 35454855, 2022). "Moreover, PTHrP derived from Lewis lung carcinoma (LLC) tumors triggers adipose tissue browning with increased energy production via activation of uncoupling protein 1 (UCP1) and cancer cachexia via binding to PTHR." (PMID 33510128, 2021).
lipoma (2 papers, 2014 to 2019). A benign, usually painless, well-circumscribed lipomatous tumor composed of adipose tissue. "Patients with a specific mtDNA mutation, m.8344A>G, show multiple symmetric lipomas, which have recently been reported to contain UCP1-positive adipocytes, typical for BAT." (PMID 24711540, 2014). "UCP1-mRNA expression in lipomas of multiple symmetric lipomatosis, bearing pathogenic mitochondrial mutations has been reported, but UCP1 expression in simple lipomas or lipoma subtypes has not been identified." (PMID 31114671, 2019). "UCP1 expression was not seen in benign lipomas including those containing non-adipose connective tissue elements such as fibrolipoma and angiolipoma." (PMID 31114671, 2019). "In contrast to BAT cells in hibernoma, mature WAT cells in simple benign lipoma and in the various lipoma subtypes were UCP1-negative." (PMID 31114671, 2019). "Hibernoma, however, is distinguished from lesions such as spindle cell/pleomorphic lipoma and haemosiderin fibrohistiocytic lipomatous tumour by the absence of CD34 expression and staining for UCP1 (at high dilution of the antibody)." (PMID 31114671, 2019).
liposarcoma (2 papers, 2019 to 2024). A usually painless malignant tumor that arises from adipose tissue. "Absence of UCP1 expression in other adipose tumours (with the exception of a few pleomorphic liposarcomas) suggests that these tumours are derived from WAT." (PMID 31114671, 2019). "Tumour cells in most high-grade pleomorphic liposarcomas were UCP1 negative, but it was noted that vacuolated tumour cells in a few pleomorphic liposarcomas stained for UCP1." (PMID 31114671, 2019). "Hibernoma-like cells have been described in well-differentiated liposarcoma and myxoid liposarcoma, but we did not identify UCP1 expression in these lesions." (PMID 31114671, 2019). "Lipoblasts and WAT cells in lipoblastoma as well as in atypical lipoamtous tumour/well-differentiated liposarcoma were also negative for UCP1." (PMID 31114671, 2019). "Most high-grade pleomorphic liposarcomas did not express UCP1 but in a minority of pleomorphic liposarcomas, scattered small and large vacuolated tumour cells expressed UCP1." (PMID 31114671, 2019). "No expression of UCP1 was noted in sections of atypical lipomatous tumour (ALT)/well-differentiated liposarcoma in extra-abdominal soft tissues or the retroperitoneum." (PMID 31114671, 2019). "There are a few reports of UCP1 expression by tumour cells in liposarcoma, but immunophenotypic expression of UCP1 in malignant adipose tumours has not been characterised." (PMID 31114671, 2019). "Both the well-differentiated liposarcoma and spindle cell sarcoma components of dedifferentiated liposarcoma were UCP1 negative." (PMID 31114671, 2019). "Both the well-differentiated liposarcoma and malignant spindle cell sarcoma components of dedifferentiated liposarcoma were negative for UCP1." (PMID 31114671, 2019). "UCP1 is strongly expressed in BAT but not WAT and is found in all hibernomas and a few pleomorphic liposarcomas but not in other adipose tumours." (PMID 31114671, 2019).
motor neuron disease (2 papers, 2009 to 2017). "Finally, muscle-restricted overexpression of uncoupling protein 1 (UCP-1) leads to age-associated neurodegeneration of neuromuscular junction (NMJ) worsening motor neuron disease in SOD1 mice." (PMID 29081604, 2017).
myocardial infarction (2 papers, 2014 to 2025). Gross necrosis of the myocardium, as a result of interruption of the blood supply to the area, as in coronary thrombosis. "UCP1 plays a critical role in activating BMP3b, which is closely associated with improved outcomes in myocardial infarction." (PMID 41207916, 2025).
non-alcoholic steatohepatitis (2 papers, 2017 to 2021). "In conclusion, succinate promotes WAT browning by enhancing Ucp1-dependent thermogenesis and indirectly ameliorates liver inflammation and non-alcoholic steatohepatitis (NASH)." (PMID 34768943, 2021).
Ovarian failure (2 papers, 2016 to 2018). "For instance, it was shown that the induction of Ucp1 by CL‐316,243 in mouse gWAT was compromised by experimental ovarian failure." (PMID 29973382, 2018). "Controls and mice with chemically induced ovarian failure were treated with CL, and TH and UCP1 protein levels were determined by immunoblot analysis." (PMID 27990249, 2016). "Ovarian failure induced by 4-vinylcyclohexene diepoxide treatment dramatically reduced BDNF and TH expression in gWAT, eliminated induction of UCP1 by CL, and reduced tissue metabolic rate." (PMID 27990249, 2016).
overnutrition (2 papers, 2012 to 2021). An imbalanced nutritional status resulting from excessive intake of nutrients. "The increased BAT size and UCP1 protein expression in obese mice fed high-Ca was reminiscent of that seen in cafeteria fed rats, and this might be explained teleologically as a physiological adaptation to overnutrition." (PMID 22269778, 2012). "Therefore, accompanied by lower levels of UCP1, PRDM16, and PGC1α mRNAs in HIGH fetuses, it is suggested that the manipulation of maternal nutrition, especially long-term maternal overnutrition, might adversely affect brown adipose tissue mass and its function in adipose depots of the fetus." (PMID 35178028, 2021).
proliferative diabetic retinopathy (2 papers, 2017 to 2021). Advanced retinopathy due to diabetes mellitus characterized by the formation of new vessels in the retina. "In the subgroup analyses on the stage of DR, allele G of UCP1 rs1800592 significantly increased the susceptibility of proliferative diabetic retinopathy (PDR) in type-2 DM patients in the allelic (OR = 1.26, P = 0.03) and homozygous models (OR = 1.60, P = 0.04)." (PMID 33579234, 2021).
renal fibrosis (2 papers, 2023). A final common manifestation of a wide variety of chronic kidney diseases characterized by glomerulosclerosis and tubulointerstitial fibrosis. "Further studies discover that UCP1 overexpression and CL316243 treatments (UCP1 agonists) reversed EMT and extracellular matrix (ECM) accumulation in renal fibrosis models in vivo and in vitro." (PMID 37533052, 2023).
Simpson-Golabi-Behmel syndrome (2 papers, 2019 to 2022). Simpson-Golabi-Behmel syndrome is a rare X-linked multiple congenital anomalies syndrome, characterized by pre- and postnatal overgrowth, distinctive craniofacial features, variable congenital malformations, organomegaly and an increased tumor risk. "Subsequently, the role of bile acids in energy expenditure was investigated in a human brown fat cell line using the Simpson-Golabi-Behmel syndrome (SGBS) preadipocyte cell line, which has high UCP1 expression levels when fully differentiated." (PMID 31237863, 2019).
thyroid cancer (2 papers, 2019 to 2022). "In a thyroid cancer patient case study, [18F]FDG-PET/CT scanning revealed that T4 supplementation for 14 days increased radioactive glucose uptake and UCP-1 expression in suprascapular BAT and subcutaneous WAT regions." (PMID 31346342, 2019).
type 1 diabetes (2 papers, 2020 to 2026). "Elevated vascular permeability has been reported in the skin of STZ-treated rats, hyperglycemic and hyperinsulinemic UCP1/DTA transgenic mice, and in patients with type 1 diabetes." (PMID 41511372, 2026).
acute leukemia (1 paper, 2024). A clonal (malignant) hematopoietic disorder with an acute onset, affecting the bone marrow and the peripheral blood. "Similarly, the genetic deletion of UCP1, the key component for mediating NST, also abolished the suppression of acute leukemias." (PMID 39049685, 2024).
acute pancreatitis (1 paper, 2025). An acute inflammatory process that leads to necrosis of the pancreatic parenchyma. "This study identifies Naa10p as a key regulator in acute pancreatitis, linking its elevated expression to decreased UCP1 levels, mitochondrial dysfunction, and enhanced inflammation." (PMID 40557397, 2025). "Naa10p disrupts the protective mitochondrial UCP1 pathway in acute pancreatitis (AP)." (PMID 40557397, 2025).
alveolar soft part sarcoma (1 paper, 2019). An alveolar soft part sarcoma occurring in adults. "Weak staining for UCP1 at this dilution was also noted in some tumour cells of a few other soft tissue sarcomas including alveolar soft part sarcoma, biphasic synovial sarcoma and undifferentiated pleomorphic sarcoma." (PMID 31114671, 2019). "UCP1 was variably expressed by tumour cells in a few non-adipose sarcomas including leiomyosarcoma, rhabdomyosarcoma, alveolar soft part sarcoma, synovial sarcoma and clear cell sarcoma." (PMID 31114671, 2019).
amyotrophic lateral sclerosis (1 paper, 2009). Amyotrophic lateral sclerosis (ALS) is a neurodegenerative disease characterized by progressive muscular paralysis reflecting degeneration of motor neurons in the primary motor cortex, corticospinal tracts, brainstem and spinal cord. "To further explore the negative influence of muscle mitochondrial uncoupling on motor neuron degeneration, we analysed whether muscle UCP1 overexpression could change the pattern of disease in a transgenic mouse model of amyotrophic lateral sclerosis (ALS)." (PMID 19404401, 2009).
anxiety disorder (1 paper, 2022). A category of psychiatric disorders which are characterized by anxious feelings or fear often accompanied by physical symptoms associated with anxiety. "Against this background, and considering the important involvement of catecholamines in the regulation of emotions, specifically their relevance to fear and anxiety disorders, we tested whether circulating levels of Epi and nor-Epi were differing between UCP-1 KO mice and WT controls." (PMID 36194650, 2022).
atrial fibrillation (1 paper, 2022). A disorder characterized by an electrocardiographic finding of a supraventricular arrhythmia characterized by the replacement of consistent P waves by rapid oscillations or fibrillatory waves that vary in size, shape and timing and are accompanied by an irregular ventricular response. "Given that low levels of UCP-1 have been linked with atrial fibrillation (AF), it has been postulated that EAT, by expressing UCP-1, may also protect against hypothermia-induced fatal arrhythmia." (PMID 34890279, 2022).
autism (1 paper, 2025). Persistent deficits in social interaction and communication and interaction as well as a markedly restricted repertoire of activity and interest as well as repetitive patterns of behavior. "This leads to transcriptional activation of uncoupling protein 1 (UCP1), suppression of neuronal apoptosis, and amelioration of autism‐like behaviors." (PMID 41244006, 2025).
chronic kidney disease (1 paper, 2025). Impairment of the renal function secondary to chronic kidney damage persisting for three or more months. "Additionally, elevated UCP1 levels have been reported to reduce oxidative stress by stabilizing SIRT3, ultimately alleviating renal interstitial fibrosis in chronic kidney disease." (PMID 40120980, 2025).
colitis (1 paper, 2021). Inflammation of the colon. "The protein expression level of UCP1 was also significantly decreased in SAT of colitis mice." (PMID 33674694, 2021). "DSS-induced colitis mice showed significantly decreased expressions of PPARα, PGC-1α, and thermogenic genes including ND5, Prdm16, Cidea, Elovl3, Dio2, and UCP1 both in SAT and BAT compared to non-colitis control mice." (PMID 33674694, 2021).
coronary atherosclerosis (1 paper, 2021). Atherosclerosis of the coronary vasculature. "Furthermore, UCP1 knockin pigs (which lack endogenous UCP1) are refractory to vascular inflammation and coronary atherosclerosis." (PMID 34878840, 2021).
dengue (1 paper, 2025). "As PPAR-γ and PGC-1α crosstalk plays a significant role in mitochondrial biogenesis along with PGC-1α transcription and enhanced thermogenesis via uncoupling protein 1(UCP1) activation, dengue-induced downregulation of these two controllers drastically hampers biogenesis." (PMID 41009534, 2025).
depression (1 paper, 2022). "We therefore next explored depression-related behavioral despair in UCP-1 KO mice in the FST." (PMID 36194650, 2022).
endocarditis (1 paper, 2017). Inflammation of the endocardium. "However, we could exclude this possible mechanism by showing that UCP-1, one of the most prominent and highly specific markers of brown adipose tissue, was not induced in adipose tissue in endocarditis animals." (PMID 28428684, 2017).
energy metabolism disorder (1 paper, 2025). "Graphene-FIR therapy activated the thermogenic program in adipose tissue, increasing the expression of UCP1 and GLUT4, activating the AMPK/PGC-1α/SIRT1 pathway in BAT and iWAT, and improving energy metabolism disorder in HFD mice." (PMID 40076847, 2025). "The therapy activated the AMPK/PGC-1α/SIRT1 pathway in adipose tissue, increasing the expression of uncoupling protein 1 (UCP1) and glucose transporter protein four (GLUT4), activating the thermogenic program in adipose tissue, and improving energy metabolism disorder in HFD mice." (PMID 40076847, 2025). "Further, graphene-FIR therapy activated the thermogenic program in adipose tissue, increasing the expression of UCP1 and glucose transporter protein four (GLUT4), activating the AMPK/PGC-1α/SIRT1 pathway in iWAT and BAT, and improving energy metabolism disorder in HFD mice." (PMID 40076847, 2025).
fibromatosis (1 paper, 2019). A poorly circumscribed neoplasm arising from the soft tissues. "Benign fibrohistiocytic tumours and fibroblastic/myofibroblastic lesions such as myofibroma, nodular fascitiis and fibromatosis were also UCP1 negative." (PMID 31114671, 2019).
fibrosis (1 paper, 2025). the formation of excess fibrous connective tissue in an organ or tissue in a reparative or reactive process. "The number of mice per cage indeed influences thermoregulation through regulation of Ucp1 expression in the BAT42 and grouped housing is one of the key experimental conditions influencing MASH-fibrosis development in rodents." (PMID 40894885, 2025).
Hearing impairment (1 paper, 2014). A decreased magnitude of the sensory perception of sound. "Data were analyzed to assess the effects of UCP1 A-3826G and UCP2 Ala55Val polymorphisms on hearing impairment." (PMID 25140308, 2014). "The UCP1 A3826G polymorphism did not exhibit any significant association with ARHI; however, the UCP2 Ala55Val polymorphism did show a significant association with hearing impairment under the dominant, recessive, and additive models (P < 0.05)." (PMID 25140308, 2014).
hepatoma (1 paper, 2010). "The mRNA abundance of PPARα-target genes that control fatty acid oxidation, such as CYP4A11, ACOX, and UCP1 significantly increases in human hepatoma cells." (PMID 20811644, 2010).
Hernia (1 paper, 2015). "Of note, one subcutaneous UCP1histological- sample from a hernia repair showed a strong UCP1 expression, which was comparable to the expression in UCP1histological+ samples (black square)." (PMID 25706927, 2015).
hyperandrogenemia (1 paper, 2020). "Androgen treatment attenuates the β-adrenoceptor-stimulated increase in UCP1 in IMBATs and provides a molecular explanation for the link between hyperandrogenemia and reduced thermogenic capacity." (PMID 33383677, 2020).
Hypoglycemia (1 paper, 2021). A decreased concentration of glucose in the blood. "In addition to the neurological phenotype, Asc-1 knockout mice show a complex metabolic phenotype with reduced body size and weight, hepatosteatosis, hypoglycemia, and reduced body temperature, the latter most likely due to a strong decrease in Ucp1 expression in brown fat." (PMID 33707431, 2021).
Hypothermia (1 paper, 2017). Reduced body temperature due to failed thermoregulation. "Hypothermia induced by KD did not affect thermogenic genes such as Sarcolipin and Pgc1a in muscles and Ucp1 in adipose tissues." (PMID 28588221, 2017).
infarction (1 paper, 2024). A localised pathological necrosis of tissue resulting from obstruction of the blood supply usually by a thrombus, an embolus, or vascular torsion. "Brown fat from the UCP1-KO mice acclimated to cold displays some analogy with the post-infarction heart." (PMID 38367663, 2024).
inflammatory skin disease (1 paper, 2025). Inflammatory skin disorders covers a broad category that includes many conditions ranging in severity, from mild itching to grave medical health complications These disorders are common in people of all ages and races. "As the primary aim of this study was to determine the role of UCP1 in psoriasis patients, other inflammatory skin diseases were not considered." (PMID 40104293, 2025).
kidney failure (1 paper, 2020). An acute or chronic condition that is characterized by the inability of the kidneys to adequately filter the blood. "Urine creatinine and albumin concentration were not elevated in UCP1 KO mice, excluding kidney failure as cause for increased water intake, which is in line with previous observations." (PMID 32005798, 2020).
leiomyosarcoma (1 paper, 2019). An uncommon, aggressive malignant smooth muscle neoplasm, usually occurring in post-menopausal women. "It is possible that expression of UCP1 in rhabdomyosarcoma, leiomyosarcoma and in a few other sarcomas may reflect origin of tumour cells from a mesenchymal stem cell precursor exhibiting an uncoupled mitochondrial phenotype." (PMID 31114671, 2019). "UCP1 was not expressed in non-adipose tissues and was not seen in benign, non-adipose soft tissue tumours, but was found in some non-adipose soft tissue sarcomas, notably rhabdomyosarcoma and leiomyosarcoma." (PMID 31114671, 2019). "Most malignant (non-adipose) mesenchymal soft tissue neoplasms did not stain for UCP1, but it was noted that tumour cells in a few leiomyosarcomas and alveolar and pleomorphic rhabdomyosarcomas stained strongly for UCP1 when the polyclonal antibody was diluted 1:500 or less." (PMID 31114671, 2019).
lipoblastoma (1 paper, 2019). A lipoma usually occurring in the extremities of young children (usually boys). "Both lipoblasts and WAT cells in lipoblastoma were UCP1-negative." (PMID 31114671, 2019).
lupus (1 paper, 2023). "Adipogenic (PPARγ) and thermogenic (UCP1) marker gene expression was significantly decreased in PVAT from lupus mice." (PMID 37006244, 2023). "Interestingly, mice with active lupus exhibit loss of thermogenic activity in PVAT, as evidenced by reduced expression of UCP1 and phenotypic “whitening,” characterized by reduced multilocular lipid droplets and increased adipocyte size." (PMID 37006244, 2023). "In addition, expression of UCP1, a brown/beige adipose marker, was dramatically decreased, while CD45-positive leukocyte infiltration was increased, in PVAT from lupus mice." (PMID 37006244, 2023).
Myocardial fibrosis (1 paper, 2022). "ISO treatment induced worse left ventricle (LV) hypertrophy, myocardial fibrosis, increased higher cTnI, CK-MB and MDA and decreased lower SOD level in Ucp1−/− rats compared with that of WT rats." (PMID 34709566, 2022).
myxoid liposarcoma (1 paper, 2019). A liposarcoma characterized by the presence of round non-lipogenic primitive mesenchymal cells and small signet ring lipoblasts within a myxoid stoma with a branching vascular pattern. "Vacuolated small fat cells and lipoblast-like cells in myxoid liposarcoma did not stain for UCP1." (PMID 31114671, 2019).
nutritional disease (1 paper, 2017). "UCP1 (ENSP00000262999), the uncoupling protein 1, has been confirmed to further participate in the pathogenesis of abnormal gastric emptying and gut hormone release processes, confirming its potential biological functions for nutritional disease." (PMID 29258237, 2017).